RAP1BP2 (RAP1B pseudogene 2)
Gene: Processed pseudogene on chromosome 3 (104,063,039 to 104,063,582, forward strand). Ensembl gene ENSG00000214405.
Diseases named in the same sentence as RAP1BP2 in open-access papers:
RAP1BP2 is named in the same sentence as 1 disease in open-access papers, as found by Europe PMC text mining. Sharing a sentence is not in itself a finding about the gene and the disease. The quoted sentences say what the papers report.
endometriosis (1 paper, 2020). The growth of functional endometrial tissue in anatomic sites outside the uterine body. "Of the previously reported variants associated with endometriosis, most had the directionally concordant effect except for rs1250241, chr2:g.216 295312 T > A at 2q35, FN1, rs517875, chr3:g.174350886 C > A at 3q13, RAP1BP2, and rs13271465, chr8:g.17282411 T > C at 8p22, MTMR7/ADAM24P." (PMID 31488892, 2020).